MAFG-AS1 (MAFG antisense RNA 1)
Gene: Long non-coding RNA gene on chromosome 17 (81,922,899 to 81,924,511, forward strand). Ensembl gene ENSG00000264769.
Diseases named in the same sentence as MAFG-AS1 in open-access papers:
MAFG-AS1 is named in the same sentence as 5 diseases in open-access papers, as found by Europe PMC text mining. Sharing a sentence is not in itself a finding about the gene and the disease. The quoted sentences say what the papers report.
bladder cancer (1 paper, 2024). "In conclusion, this study highlights the critical role of the MAFG-AS1/UCHL5/PCBP2/FPN1 axis in cisplatin resistance in bladder cancer, suggesting that inhibition of MAFG-AS1 may promote ferroptosis and enhance cellular sensitivity to cisplatin treatment." (PMID 39544949, 2024).
breast carcinoma (1 paper, 2021). "Many lncRNAs are implicated in breast cancer oncogenicity, e.g., MAFG-AS1, LINC00466, and LINC00649 lncRNAs are overexpressed in breast cancer, exerting pro-oncogenic effects." (PMID 37303942, 2021).
prostate carcinoma (1 paper, 2022). A carcinoma that arises from epithelial cells of the prostate gland. "Consistently, MAFG-AS1 high expression was significantly correlated with poor prognosis in patients with prostate cancer patients." (PMID 35992831, 2022). "Collectively, these results suggest that MAFG-AS1 may be involved in ribosome biogenesis to regulate prostate cancer tumorigenicity." (PMID 35992831, 2022). "Furthermore, MAFG-AS1 knockdown by siRNA markedly impaired prostate cancer cell proliferation, migration, and invasion." (PMID 35992831, 2022).
tumor (2 papers, 2020 to 2021). "Overall, these results concluded that MAFG-AS1 knockdown inhibited the proliferation, migration, invasion, and tumor growth of drug-resistant HCC cells in vitro, suggesting the potential tumor-promoting role of MAFG-AS1 in drug resistance of HCC." (PMID 34386494, 2021). "After knocking down MAFG‐AS1, the tumor‐forming ability of the cells was decreased, the EMT process was inhibited; in sharp contrast, overexpression of MAFG‐AS1 exerted a significant promoting effect on tumor growth and EMT process." (PMID 33377647, 2020).
MAFG-AS1 also shares sentences with these, for which no sentence is quoted: liver cancer (1 paper).